BRF1 (BRF1 general transcription factor IIIB subunit)
Diseases named in the same sentence as BRF1 in open-access papers (continued):
Sharing a sentence is not in itself a finding about the gene and the disease.
lung carcinoma (2 papers, 2021 to 2023). "The AUC result indicates that the accuracy of high Brf1 expression is a little low as a diagnostic biomarker for lung cancer." (PMID 33995823, 2021). "This implies that ROS and AMPK are potentially involved in Brf1 expression, which may be associated with lung cancer." (PMID 33995823, 2021). "This points out that there may be an underlying relationship between Brf1 and lung cancer." (PMID 33995823, 2021). "The study identifies a new pathway, pAMPKα, which modulates Brf1, tRNAs, and 5S rRNA transcription in lung cancer cells." (PMID 33995823, 2021). "Here, we report, for the first time, that Brf1 expression is enhanced in human cases of lung cancer." (PMID 33995823, 2021). "The overall reaction of Brf1 staining in tumor foci of lung cancer is markedly higher than that in paracarcinoma tissue." (PMID 33995823, 2021). "To test Brf1 expression in the cases of lung cancer, we utilized the samples of this disease to determine the levels of Brf1 expression in tumor foci and paracarcinoma tissues by immunohistochemistry (IHC) staining." (PMID 33995823, 2021). "Together, these studies indicate that Brf1 is overexpressed in lung cancer patients, and as a result, high expression of Brf1 reveals a worse prognosis." (PMID 33995823, 2021). "The result shows that about 60% of cases of lung cancer with high Brf1 expression display significant short overall survival times." (PMID 33995823, 2021). "These outcomes demonstrate that high Brf1 expression reveals a worse prognosis in lung cancer patients." (PMID 33995823, 2021). "In the present study, we report that Brf1 expression is increased in the cases of human lung cancer." (PMID 33995823, 2021). "Since MNNG enhances Brf1 promoter activity in A549 cells, similar results are also observed in the lung cancer cell line, H1975." (PMID 33995823, 2021). "A recent study also indicates that levels of ROS of lung cancer cells are associated with the alteration of pAMPKα, while AMPK activation is associated with protein synthesis, which is controlled by Brf1 and Pol III genes." (PMID 33995823, 2021). "Brf1 overexpression in lung cancer cases is accompanied by higher pAMPKα levels." (PMID 33995823, 2021). "In addition, we also determined the cellular levels of Brf1 in the bronchial epithelial cells and lung cancer cell lines of humans." (PMID 33995823, 2021). "Here, we report that Brf1 is overexpressed in cases of lung cancer." (PMID 33995823, 2021). "However, it remains to be detected if Brf1 expression is increased in human cases of lung cancer and what is the significance of its expressional status in the diagnosis and prognosis of this disease." (PMID 33995823, 2021). "The overexpression of Brf1 is accompanied by a high level of pAMPKα in the cases of lung cancer." (PMID 33995823, 2021). "This shows that both Brf1 and pAMPKα play an important role in lung cancer." (PMID 33995823, 2021). "Here, we report that Brf1 expression was enhanced in the cases of lung cancer (–3)." (PMID 33995823, 2021). "Brf1 and pAMPKα are colocalized in lung cancer cell nuclei, which maybe synergistically regulate the transcription of Pol III genes." (PMID 33995823, 2021). "In summary, our studies demonstrate that Brf1 is overexpressed in human lung cancer." (PMID 33995823, 2021). "High Brf1 expression is consistent with pAMPKα elevation in tumor tissues of lung cancer." (PMID 33995823, 2021). "It proves the direct relationship between Brf1 and lung cancer." (PMID 33995823, 2021). "It suggests that Brf1 is a novel prognostic biomarker for human lung cancer." (PMID 33995823, 2021). "Given Brf1 expression with high levels of pAMPKα in the cases of human lung cancer, we further determine whether pAMPKα mediates Brf1 expression and Pol III gene transcription." (PMID 33995823, 2021). "Brf1 and pAMPKα are colocalized in nuclei of lung cancer cells, which suggests that Brf1 and pAMPKα may synergistically modulate the activities of Pol III genes." (PMID 33995823, 2021).
lung carcinoma (continued). "Furthermore, we determined the relationship between Brf1 expression and the overall survival period of lung cancer patients." (PMID 33995823, 2021). "Brf1 may be a biomarker for establishing the prognosis of lung cancer." (PMID 33995823, 2021). "To test this hypothesis, we collected samples of human lung cancer to detect the levels of Brf1 proteins and phosphorylated AMPKα (pAMPKα) by immunoblot analysis and explore the correlation of the levels of pAMPKα with Brf1 expression." (PMID 33995823, 2021). "pAMPKα-mediated dysregulation of Brf1 and Pol III genes plays important roles in cell proliferation, colony formation, and tumor development of lung cancer." (PMID 33995823, 2021). "In contrast, inhibiting pAMPKα decreases cellular levels of Brf1, resulting in the reduction of Pol III gene transcription to attenuate the rates of cell proliferation and colony formation of lung cancer cells." (PMID 33995823, 2021). "It is a new mechanism that pAMPKα mediates dysregulation of Brf1 and Pol III genes to promote lung cancer development." (PMID 33995823, 2021). "On the other hand, LKB1 activates AMPK activity, while activated AMPKα upregulates Brf1 and Pol III gene transcription to promote lung cancer development in the status of K-Ras activation." (PMID 33995823, 2021). "It shows that there is a new and much more important pathway, namely, pAMPKα, which upregulates the activities of Brf1 and Pol III genes to promote human lung cancer development except AMPK-mediated Tfe3." (PMID 33995823, 2021). "Activated AMPK may be detected by its phosphorylation antibody in lung cancer samples, while the activated AMPK may mediate Brf1 expression and Pol III gene transcription." (PMID 33995823, 2021). "We used four levels of intensity of Brf1 expression: negative staining, weak staining, moderate staining, and strong staining in these cases of lung cancer." (PMID 33995823, 2021). "The immunoblot analysis reveals that the cellular levels of Brf1 in lung cancer cell lines, A549 and H1975, are higher than those in no lesion bronchial epithelial cell line, 16HBE." (PMID 33995823, 2021). "Here, we have further investigated the relationship of the abnormal expression of Brf1 with a high level of phosphorylated AMPKα (pAMPKα) and explored the role and molecular mechanism of pAMPKα-mediated dysregulation of Brf1 and Pol III genes in lung cancer." (PMID 33995823, 2021). "Therefore, we further determine the colocalization of Brf1 and pAMPKα in MNNG-treated lung cancer cells." (PMID 33995823, 2021). "The results indicate that Brf1 expression is significantly increased in tumor tissues of lung cancer, compared to adjacent noncancerous tissue (ANT) samples in the same case." (PMID 33995823, 2021). "To date, no studies elucidate the roles of dysregulation of TF IIB-related factor 1 (Brf1) and its target genes, RNA polymerase III-dependent genes (Pol III genes) in lung cancer development, whereas dysregulation of Brf1 and Pol III genes is tightly related to tumor development." (PMID 33995823, 2021).
benign prostatic hyperplasia (1 paper, 2020). A non-cancerous nodular enlargement of the prostate gland. "BRF1 immunoreactivity was studied in 516 PCa cases and 134 benign prostatic hyperplasia (BPH) controls." (PMID 31740786, 2020).
Breast Tumor (1 paper, 2019). "However, little is known about the role of alcohol in Brf1 (TFIIIB-related factor 1) expression and Pol III gene (RNA polymerase III-dependent gene) transcription during breast tumor development." (PMID 31781337, 2019).
cardiac hypertrophy (1 paper, 2019). "We found that both RNA pol III inhibitor and U0126 inhibited the expression of 5SrRNA, tRNALeu and Brf1 and improved Maf1 knockdown-promoted cardiac hypertrophy." (PMID 31695767, 2019).
cervical cancer (1 paper, 2008). A primary or metastatic malignant neoplasm involving the cervix. "Interestingly, the Brf1 protein levels did not vary considerably in HeLa, MCF-7 and DU-145 cells, yet Brf1 mRNA expression varied considerably in breast, prostate and cervical cancer cell lines tested." (PMID 18700021, 2008).
kidney tumors (1 paper, 2020). "The BRF1 gene is located in a chromosomal region showing significant allelic loss in different tumors, and indeed, decreased BRF1 mRNA levels were observed in 50% of the kidney tumors and 23% of the rectal tumors investigated." (PMID 32611613, 2020).
leukodystrophies (1 paper, 2025). "These two, as well as other RNA polymerase III subunits, were also linked to hypomyelination leukodystrophies, while BRF1, the BRF2 paralog, was associated with CFDS." (PMID 40229899, 2025).
liver cancer (1 paper, 2024). An epithelial or non-epithelial malignant neoplasm that arises from the liver. "Our results suggest that in the microenvironment of liver cancer, an increase in Brf1 may promote the expression of Bcl-2, thereby promoting the proliferation of liver cancer cells and inhibiting their apoptosis." (PMID 39308682, 2024).
liver failure (1 paper, 2024). A liver disease characterized by the liver losing or has lost all of its function. "Brf1 knockout led to liver failure and hepatocyte apoptosis in mice." (PMID 39308682, 2024).
ovarian carcinoma (1 paper, 2023). A malignant neoplasm originating from the surface ovarian epithelium. "BDP1 mRNA expression was significantly decreased in ovarian cancer, p = 0.01 but the expression of other TFIIIB subunits, BRF1, BRF2, and TBP, was not significantly changed." (PMID 36305848, 2023).
pancreatic cancer (1 paper, 2019). "We next analysed the role of Brf1 in pancreatic tumour development where heterozygosity for c-Myc strongly suppresses pancreatic cancer formation." (PMID 30858608, 2019).
pancreatic ductal adenocarcinoma (1 paper, 2024). An infiltrating adenocarcinoma that arises from the epithelial cells of the pancreas. "For instance, cg25927164 (RAI1) and cg16561543 (BRF1) were hypermethylated in muscle-invasive bladder cancer and pancreatic ductal adenocarcinoma, respectively." (PMID 38336771, 2024).
prostate adenocarcinoma (1 paper, 2020). "Utilising the Memorial Sloan-Kettering Cancer Center (MSKCC) (2010) and The Cancer Genome Atlas (TCGA) (provisional) prostate adenocarcinoma datasets in cBioPortal, elevated BRF1 expression also associated with poor outcome." (PMID 31740786, 2020).
prostate tumours (1 paper, 2020). "Quantitative real-time PCR (qPCR) was performed using primers specific for human BRF1 confirmed its overexpression in PtenΔ/ΔBRF1Tg prostate tumours (p = 0.0459)." (PMID 31740786, 2020).
serous ovarian cancer (1 paper, 2023). "We sought to determine if the observed alterations in BDP1 in serous ovarian cancer are unique to BDP1 or are a common feature in all TFIIIB subunits including, BRF1, BRF2, and TBP which have been previously shown to be deregulated in cancer." (PMID 36305848, 2023).
steatosis (1 paper, 2025). Increased lipid within the cytoplasm of cells. "Liver-specific Zfp36l1KO mice showed protection against the development of steatosis after a Lieber–DeCarli liquid diet, as well as an increase in FGF21 mRNA, a protective factor of steatosis, which is directly inhibited by BRF1." (PMID 39941720, 2025). "Regarding the other TTP family members (i.e., BRF1 and BRF2), only one study has demonstrated that mice depleted for ZFP36L1 are protected from diet-induced obesity and steatosis via an impaired lipid absorption regulation of Cyp7a1 (cholesterol 7α-hydroxylase) and the bile acid level." (PMID 39941720, 2025).
systemic sclerosis (1 paper, 2014). A chronic disorder, possibly autoimmune, marked by excessive production of collagen which results in hardening and thickening of body tissues. "RNAP-III is an autoantigen specific to Systemic Sclerosis (SSc); BRF1 thus encodes a peri-antigen for SSc." (PMID 24988487, 2014).
cancer (18 papers, 2008 to 2024). A tumor composed of atypical neoplastic, often pleomorphic cells that invade other tissues. "This feature provides the possibility of elucidating a common mechanism of alcohol-associated human cancers by determining deregulation of Brf1 and Pol III genes." (PMID 26701855, 2016). "This suggests that the high level of Brf1 reflects the oncogenesis status of cells and Brf1 may be a novel biomarker for cancers, whereas alcohol-caused deregulation of Brf1 and Pol III genes may be a common mechanism of alcohol-associated cancers." (PMID 26701855, 2016). "Brf1 expression had low specificity, including tissue specificity, cell type specificity, organ specificity, and cancer specificity." (PMID 39308682, 2024). "Recent studies indicate that Brf1 expression is increased in human cancers of the liver, breast, stomach, and prostate." (PMID 33995823, 2021). "This indicates that the abnormal expression of Brf1 links to human cancers and high Brf1 expression predicts worse prognosis of HCC." (PMID 31781337, 2019). "It looks strange, as high Brf1 expression in cancer patients should possess short survival times usually." (PMID 31781337, 2019). "We also found the trend that the patients with high Brf1 expression reveal short OS period in other cancers (unpublished)." (PMID 31781337, 2019). "We also demonstrate, that Brf1-dependent VAI transcription was significantly higher than the Brf2-dependent U6 snRNA transcription in all cancer cell lines tested." (PMID 18700021, 2008). "We demonstrate that Brf1 and Brf2 mRNA are differentially expressed in a variety of cancer cells and that the Brf2 promoter is more active than the Brf1 promoter in all cell lines tested." (PMID 18700021, 2008). "We have demonstrated that the TFIIIB subunits Brf1 and Brf2 are differentially expressed at the mRNA level in a variety of cancer cells." (PMID 18700021, 2008). "Here, we report that the TFIIIB subunits Brf1 and Brf2 are differentially expressed in a variety of cancer cell lines." (PMID 18700021, 2008). "This shows that Brf1 plays an important role in human cancer development and tumor growth." (PMID 33995823, 2021). "This implies that Brf1 overexpression is required for cancer cell growth in humans." (PMID 33995823, 2021). "Similarly to TTP, BRF1 binds to mRNAs through a tandem zinc finger domain with a double zinc finger motif, it promotes the mRNA decay of various cancer-related transcripts (e.g., VEGFA), and its expression is reduced in several cancers." (PMID 34502337, 2021). "Therefore, we were unable to find a limiting role for Brf1 activity in cancer despite the large number of studies showing Pol-III deregulation." (PMID 30858608, 2019). "This could potentially account for the ability of cancers with BDP1 homodeletions to continue with RNA pol III transcription in its absence as these regulators would have direct interaction with an already formed BRF1‐TBP complex." (PMID 36305848, 2023). "TFIIIB, an RNA polymerase III specific transcription factor has been found to be deregulated in human cancers with much of the research focused on the TBP, BRF1, and BRF2 subunits." (PMID 36305848, 2023). "BRF1 is a rate-limiting factor for RNA Polymerase III-mediated transcription and is elevated in numerous cancers." (PMID 31740786, 2020). "The group with low Brf1 expression, representing most cases of TNBC, had worse outcomes including earlier cancer recurrence and metastasis." (PMID 28972307, 2017). "It is noteworthy that another polyphenol, EGCG that is enriched in green tea, also affects expression of BRF1 and BRF2 selectively, but in this case elicits an inhibitory effect, in keeping with its anti-cancer activity." (PMID 26573593, 2015).
cancer (continued). "The TFIIIB subunits, BRF1,20, 21, 22, 23 required for gene‐internal promoters, and BRF2,12, 16, 24, 25, 26, 27, 28, 29, 30, 31, 32, 33 required for gene‐external promoters, distinguish the two forms and have been well‐studied in various human cancers." (PMID 36305848, 2023). "As enhancements of Brf1 and Pol III gene activities are tightly related to human cancers, this suggests that AMPK activation may involve the modulation of Brf1 and Pol III gene transcription to increase cell proliferation and promote tumor development." (PMID 33995823, 2021). "This revealed a sub-network linking eight transcriptional regulators of which most already have been related to cancer progression, including HDAC2, BPTF, BRF1, TAF11, TCF12, and FOS31,32, but also a prominent role for SMADs that are normally driven by TGF-β33." (PMID 31278301, 2019). "In addition, Brf1 has been shown to be a direct target of activation by c-myc and ERK, both known to play a key role in cancer pathogenesis." (PMID 18700021, 2008). "Taken together, we reason that deregulation of Brf1 and Brf2 expression could be a key mechanism responsible for the observed deregulation of RNA pol III transcription in cancer cells." (PMID 18700021, 2008). "We further demonstrate that the Brf1 and Brf2 promoters differ in activity in cancer cell lines, and VAI transcription is universally elevated, as compared to U6 snRNA transcription, in breast, prostate and cancer cell lines." (PMID 18700021, 2008). "However, we found little evidence for a role for Brf1 as a driver of cancer as tumor and normal cells appear equally reliant on its fundamental activity." (PMID 30858608, 2019). "Furthermore, we have found that alcohol increases expression of Brf1 and Pol III genes in liver and breast cell lines and the cellular levels of Brf1 in cancer cell lines are higher than in non-tumor cell lines." (PMID 26701855, 2016). "However, the levels of Brf1 expression in human cancers are not well documented." (PMID 28972307, 2017). "However, it is not clear what role of Brf1 overexpression plays in human cancers." (PMID 26701855, 2016). "Surprisingly, the Brf1 protein levels did not vary considerably in HeLa, MCF-7 and DU-145 cells, yet Brf1 mRNA expression varied considerably in the cancer cell lines tested." (PMID 18700021, 2008).